SLC1A1 (solute carrier family 1 member 1)
Description:
Sodium-dependent, high-affinity amino acid transporter that mediates the uptake of L-glutamate and also L-aspartate and D-aspartate. Can also transport L-cysteine. Functions as a symporter that transports one amino acid molecule together with two or three Na(+) ions and one proton, in parallel with the counter-transport of one K(+) ion. Mediates Cl(-) flux that is not coupled to amino acid transport; this avoids the accumulation of negative charges due to aspartate and Na(+) symport. Plays an important role in L-glutamate and L-aspartate reabsorption in renal tubuli. Plays a redundant role in the rapid removal of released glutamate from the synaptic cleft, which is essential for terminating the postsynaptic action of glutamate (By similarity). Contributes to glutathione biosynthesis and protection against oxidative stress via its role in L-glutamate and L-cysteine transport (By similarity). Negatively regulated by ARL6IP5 (By similarity).
Synonyms: EAAC1; EAAT3; HEAAC1; DCBXA; SCZD18
Tractability: Small molecule: a structure with a bound ligand is known; a high-quality ligand is known; it belongs to a druggable protein family. Antibody: UniProt places it where antibodies can reach, with high confidence; its Gene Ontology location is reachable by antibodies, with high confidence; UniProt predicts a signal peptide or a membrane-spanning region. PROTAC: ubiquitination databases record sites on it; its protein half-life has been measured; a small molecule that binds it is known.
Target class: Transporter; Electrochemical transporter; SLC superfamily of solute carriers; SLC01 family of amino acid transporters
Gene: Protein-coding gene on chromosome 9 (4,490,225 to 4,587,469, forward strand). Ensembl gene ENSG00000106688.
Subcellular location: Cell membrane; Apical cell membrane; Synapse, synaptosome; Early endosome membrane; Late endosome membrane; Recycling endosome membrane
Pathways (Reactome):
Disease: Defective SLC1A1 is implicated in schizophrenia 18 (SCZD18) and dicarboxylic aminoaciduria (DCBXA)
Neuronal System: Glutamate Neurotransmitter Release Cycle
Transport of small molecules: SLC-mediated transport of amino acids
Gene Ontology:
Molecular function: chloride transmembrane transporter activity; cysteine transmembrane transporter activity; D-aspartate transmembrane transporter activity; glutamate:sodium symporter activity; high-affinity L-glutamate transmembrane transporter activity; L-aspartate transmembrane transporter activity; L-glutamate transmembrane transporter activity; protein binding; identical protein binding; monoatomic anion channel activity; symporter activity
Biological process: chloride transmembrane transport; cysteine transport; D-aspartate import across plasma membrane; D-aspartate transmembrane transport; L-aspartate import across plasma membrane; L-aspartate transmembrane transport; L-glutamate import; L-glutamate import across plasma membrane; L-glutamate transmembrane transport; amino acid transport; blood vessel morphogenesis; chemical synaptic transmission; maintenance of blood-brain barrier; neurotransmitter transport; transepithelial transport; transport across blood-brain barrier; adult behavior; brain development; cellular response to cocaine; conditioned place preference; cysteine transmembrane transport; cytokine-mediated signaling pathway; dopamine metabolic process; exploration behavior; G protein-coupled dopamine receptor signaling pathway; and 21 more
Cellular component: apical part of cell; apical plasma membrane; axon terminus; extracellular exosome; membrane; neuronal cell body; plasma membrane; recycling endosome; synapse; apical dendrite; asymmetric synapse; axon; cell periphery; dendrite; dendritic shaft; dendritic spine; distal dendrite; early endosome membrane; glial cell projection; late endosome membrane; perikaryon; perisynaptic space; presynapse; proximal dendrite; recycling endosome membrane; and 6 more
Genetic constraint (gnomAD): Loss-of-function variants: 30 observed, 39.03 expected, observed/expected ratio (o/e) 0.77, 90% interval 0.57 to 1.04. The upper end of that interval is the gene's LOEUF score, 1.04, which puts it in group 4 of 6, group 1 being the genes least tolerant of losing a copy. Missense variants: 621 observed, 572.13 expected, observed/expected ratio (o/e) 1.09, 90% interval 1.01 to 1.16. Synonymous variants: 252 observed, 214.59 expected, observed/expected ratio (o/e) 1.17, 90% interval 1.06 to 1.3.
Gene-disease validity (ClinGen):
ClinGen rates the evidence that SLC1A1 causes each of these diseases.
dicarboxylic aminoaciduria (autosomal recessive): Limited. Dicarboxylicaminoaciduria is characterized by infantile-onset hypoglycaemia and hyperprolinaemia associated, in certain cases, with intellectual deficit.
Homologues: Orthologues: chimpanzee SLC1A1 (99% identical), macaque SLC1A1 (98% identical), pig SLC1A1 (93% identical), rabbit SLC1A1 (91% identical), rat Slc1a1 (91% identical), guinea pig SLC1A1 (90% identical), mouse Slc1a1 (90% identical), dog SLC1A1 (88% identical), tropical clawed frog slc1a1 (83% identical), zebrafish slc1a1 (74% identical). Paralogues in human: SLC1A3 (52% identical), SLC1A6 (50% identical), SLC1A2 (50% identical), SLC1A7 (47% identical), SLC1A4 (41% identical), SLC1A5 (40% identical).
Diseases named in the same sentence as SLC1A1 in open-access papers:
SLC1A1 is named in the same sentence as 96 diseases in open-access papers, as found by Europe PMC text mining. Sharing a sentence is not in itself a finding about the gene and the disease. The quoted sentences say what the papers report.
schizophrenia (23 papers, 2014 to 2025). A major psychotic disorder characterized by abnormalities in the perception or expression of reality. "The gene SLC1A1 has been shown to play a role in obsessive compulsive disorder and sterotype behaviour, as well as schizophrenia susceptibility." (PMID 38457441, 2024). "Pointing toward the evidence of association of the SLC1A1 gene with SGA-induced OCS in schizophrenia patients, Poyurovsky and collaborators suggested the possibility of a genetic predisposition, which is unmasked by SGA treatment with a different load." (PMID 37627285, 2023). "We previously reported a 84-Kb hemi-deletion copy number variant at the SLC1A1 gene locus that reduces its expression and appeared causally linked to schizophrenia." (PMID 28886095, 2017). "Overall, our results in the working memory task as well as in the morphometric and gene expression analyses support the association of Slc1a1 deficiency with cognitive impairments observed in schizophrenia." (PMID 28886095, 2017). "Given our previous finding of the association of Slc1a1 disruptions with schizophrenia, this observation further supports the idea that PPI is likely to represent the “interface of psychosis and cognition"." (PMID 28886095, 2017). "We previously reported a novel 84-Kb hemi-deletion copy number variant (CNV) in SLC1A1 that exhibits a large effect size causally linked to schizophrenia in a 5-generation family from the Pacific island of Palau." (PMID 28886095, 2017). "Additionally, studies suggest that the presence of polymorphisms in the SLC1A1/EAAC1 gene has been shown to be a risk factor for the development of OCS in patients with schizophrenia." (PMID 39849391, 2025). "Interestingly, EAAT3 striatal transcript expression is decreased in schizophrenia and SLC1A1, the gene encoding EAAT3, is a risk gene for schizophrenia." (PMID 38849515, 2024). "The DLGAP3/SLC1A1 interaction might be involved in the susceptibility to develop OCS in antipsychotic-treated schizophrenia patients." (PMID 37627285, 2023). "Thus, our observation of anxiety-like phenotype of Slc1a1+/- mice further supports the association of this gene with anxiety and its potential comorbidity with schizophrenia." (PMID 28886095, 2017). "SNPs of SLC1A1 (rs2228622) and GRIN2B (rs890) genes as well as the interaction between the two genes showed a tendency for association with OCS in schizophrenia patients receiving clozapine." (PMID 37627285, 2023). "In a cohort of 250 patients with chronic schizophrenia under clozapine treatment, the impact of SNPs in SLC1A1, Glutamate Ionotropic Receptor Kainate Type Subunit 2 (GRIK2), and N-methyl-D-aspartate receptor subunit 2B (GRIN2B) genes on OCS was assessed." (PMID 37627285, 2023). "The solute carrier family 1 member 1 (SLC1A1) gene has been consistently associated with primary OCD patients and the presence of the same SNP has been shown to increase the risk of OCS/OCD in schizophrenia with antipsychotic medications." (PMID 37029179, 2023). "Yet, the expression of SLC1A1, encoding EAAT3, has been found to be impaired in neuroinflammation-related diseases, such as multiple sclerosis, schizophrenia, hypoxia/ischemia, and epilepsy." (PMID 35323793, 2022). "One of the two miRNA target genes encoding glutamate transporters, slc1a1, has been extensively studied in the context of epilepsy, оbsessive-compulsive disorder (OCD), multiple sclerosis (MS), Alzheimer's disease, and schizophrenia." (PMID 34286132, 2021). "First, to the best of our knowledge, mutations with large risk to schizophrenia have been reported in at least five genes, DISC1, NRXN1, PRODH, SHANK3, and SLC1A1 according to records in OMIM." (PMID 30745909, 2018). "Overall, our results indicate the presence of several behavioral, biochemical, and transcriptional changes in Slc1a1+/- mice that are consistent with its potential utility in modeling schizophrenia and merit further study." (PMID 28886095, 2017).
schizophrenia (continued). "Using well-established behavioral paradigms that model aspects of schizophrenia, we found several phenotypes consistent with those seen in this disease in Slc1a1+/- mice." (PMID 28886095, 2017). "Since our report, other groups have also observed similarly localized SLC1A1 CNVs in schizophrenia probands from other populations." (PMID 28886095, 2017). "Specific genetic risk factors seem to dispose patients with schizophrenia to develop OCS and risk-conferring polymorphisms has been defined in SLC1A1, BDNF, DLGAP3, and GRIN2B and in interactions between these individual genes." (PMID 26556409, 2014). "In summary, specific genetic risk factors predispose patients with schizophrenia to develop OCS induced by antipsychotic treatment, and risk-conferring polymorphisms in genes linked to the glutamatergic system, such as SLC1A1, DLGAP3, and GRIN2B, have been identified." (PMID 37627285, 2023). "Furthermore, increased expression of SLC1A1 at both the mRNA and protein levels was demonstrated in schizophrenia patients." (PMID 34286132, 2021). "Diseases associated to SLC1A1 (OMIM: 133550) include Dicarboxylic Aminoaciduria and susceptibility to Schizophrenia, while LINGO2 (OMIM: 609793) has variants associated with essential tremor and Parkinson disease and also has an intronic SNP associated with body mass." (PMID 30677042, 2019). "When considered together, the combined genetic data suggest that uncommon CNVs of large effect involving SLC1A1 may help explain a small proportion of the incidence of schizophrenia." (PMID 28886095, 2017). "Since anxiety is a highly prevalent comorbidity of schizophrenia, we investigated whether Slc1a1-HET mice would exhibit more anxiety-like behavior, compared to WT mice." (PMID 28886095, 2017). "Parallel and multistep analysis in this research showed that SLC1A1, DRD2, DRD4, BDNF, ESR1, CDH2, GRIN2B, TNFa, GABBR1, and OLIG2 are common genes between schizophrenia and OCD which ESR1, DRD2, GABBR1, TNFa, and CDH2 are the most important individuals." (PMID 31086558, 2018).
epilepsy (15 papers, 2012 to 2025). A brain disorder characterized by episodes of abnormally increased neuronal discharge resulting in transient episodes of sensory or motor neurological dysfunction, or psychic dysfunction. "The GLUT1 deficiency syndrome (GDS) is an autosomal dominat disease caused by mutations in the solute carrier family 1 member 1 (SLC1A1) gene and is associated with many disorders including epilepsy, body movement disorders and speech impairments." (PMID 35739198, 2022). "Significant overexpression of the SLC1A1 protein and its rodent homolog was found in postmortem brain samples from patients with epilepsy and rats with pilocarpine-induced epilepsy." (PMID 34286132, 2021). "Thus, the results of our study provide further evidence for involvement of SLC1A1 in the pathobiology of epilepsy." (PMID 37865723, 2023). "Expression levels of SLC1A1, SLC25A12, ATP2B2 and their related lncRNAs were significantly different between patients with epilepsy and healthy subjects." (PMID 37865723, 2023).
obsessive-compulsive disorder (12 papers, 2011 to 2025). A disorder characterized by the presence of persistent and recurrent irrational thoughts (obsessions), resulting in marked anxiety and repetitive excessive behaviors (compulsions) as a way to try to decrease that anxiety. "SLC1A1 variants are commonly implicated in glutamargic-related neurological abnormalities like Obsessive-Compulsive Disorder and or sensory epilepsy due to contact with hot water." (PMID 34944156, 2021). "Mutations in SLC1A1 are thought to cause dicarboxylic aminoaciduria and have been associated with psychiatric disorders including psychosis, obsessive compulsive disorder, and neuronal degeneration." (PMID 26259131, 2015). "Evidence has also shown that SLC1A1/EAAT3 overexpression could cause pathologic effects on dopaminergic neurotransmission and increase the risk of obsessive-compulsive disorder (OCD)." (PMID 35323793, 2022). "As an example, the gene GLIS3, which has been implicated in diabetes and does not seem to have a major role in the brain, is actually located next to SLC1A1 (encoding the high-affinity glutamate transporter) which has been associated with obsessive-compulsive disorder and psychosis." (PMID 34326310, 2021). "Interestingly, previous research reported a correlation between the severity of the symptoms in individuals with obsessive-compulsive disorder and the mutation of the EAAT 3, solute carrier family 1 member 1 (SLC1A1) gene." (PMID 40725163, 2025). "Interestingly, SLC1A1 was the first positional candidate gene in the anxiety disorder obsessive compulsive disorder (OCD)." (PMID 28886095, 2017).
Anxiety (10 papers, 2017 to 2025). Intense feelings of nervousness, tension, or panic often arise in response to interpersonal stresses. "In addition, polymorphisms in SLC1A1 are associated with the severity of anxiety symptom in children with autism spectrum disorder." (PMID 32507125, 2020). "The results suggest that Slc1a1 deficiency might promote anxiety-like behavior in mice." (PMID 28886095, 2017). "The lack of differences in baseline OCD-relevant behavior in these mice is in contrast to the results of a recently published paper that shows significantly increased time spent grooming and enhanced anxiety-like behavior in a different line of Slc1a1-OE mice." (PMID 38514191, 2024). "While most of these works relied on the use of Slc1a1-/- mice, other studies that used overexpression models of EAAC1 showed behavioral abnormalities, including increased anxiety-like behaviors and reduced responses to amphetamine-induced hyperlocomotion." (PMID 37435808, 2023). "Overexpression of the Slc1a1/EAAT3 glutamate transporter increases anxiety-like and repetitive behaviors in mice along with cortico-striatal deficits that is decreased to normal with the treatment of fluoxetine or clomipramine." (PMID 34566718, 2021). "Alternatively, it is possible that the reduced interaction with the objects was related to reduced attention or to increased anxiety in Slc1a1+/- mice, which also spent less time in the center of the open field chamber." (PMID 28886095, 2017). "Together, these observations are consistent with a likely increase in anxiety-like behavior as a result of reduced Slc1a1 expression." (PMID 28886095, 2017). "Additionally, variations in SLC1A1 gene have also been associated with other forms of anxiety disorders, including posttraumatic stress disorder (PTSD) or anxiety symptom severity in autism spectrum disorder (ASD)." (PMID 28886095, 2017). "We found no consistent differences in grooming behavior or anxiety-like behavior between Slc1a1-OE mice and controls." (PMID 38514191, 2024). "It is worth knowing, however, that biological pathways associated with SLC1A1 and GSTZ1 seem to be related to anxiety symptoms in general, rather than to social anxiety specifically." (PMID 32507125, 2020). "Although these differences were not significant, in the OF test, Slc1a1+/- and Slc1a1-/- mice also spent significantly less time in the anxiety-provoking center zone of the chamber compared to WT mice." (PMID 28886095, 2017). "However, studies on EAAT3 heterozygous mice revealed that despite reduced expression of the Slc1a1 gene, there was no impact on anxiety-related or compulsive behaviors or neurotransmitter levels in the cortico-striatal circuit." (PMID 39851412, 2025). "Furthermore, while we previously reported no anxiety-like behavioral differences in mice lacking Slc1a1, two previous studies reported increased anxiety-like behavior in Slc1a1-KO mice, with one of these studies reporting an increased number of grooming bouts in Slc1a1-KO mice as well." (PMID 38514191, 2024).
glioma (10 papers, 2009 to 2021). A benign or malignant brain and spinal cord tumor that arises from glial cells (astrocytes, oligodendrocytes, ependymal cells). "When looking at the association between SLC1A1 and cancer types other than ccRCC, a significant correlation was observed between SLC1A1 overexpression and glioma." (PMID 30862152, 2019).
autism (7 papers, 2011 to 2025). Persistent deficits in social interaction and communication and interaction as well as a markedly restricted repertoire of activity and interest as well as repetitive patterns of behavior. "In terms of genetics, Glu transporter genes are functional candidates for autism, and single-nucleotide polymorphisms in the SLC1A1 and SLC1A2 Glu transporter genes are associated with autism (Jacob, Landeros-Weisenberger, & Leckman, 2009)." (PMID 39564744, 2024). "Glutamate transporter genes are functional candidates for autism, and single-nucleotide polymorphisms (SNPs) in SLC1A1 and SLC1A2 glutamate transporter genes are associated with autism." (PMID 35296811, 2022). "Recently, several lines of evidence derived from genetic studies have shown the strong association between EAAT3 (also known as SLC1A1, expressed in the CNS and periphery) and autism, suggesting that the EAATs may, in fact, play a part in the pathophysiology of autism." (PMID 21998651, 2011). "Two genetic studies have also demonstrated an influence of the SLC1A1 gene on autism, which is also characterized by a lack of empathy." (PMID 29304071, 2018).
Brain atrophy (7 papers, 2007 to 2025). Partial or complete wasting (loss) of brain tissue that was once present. "In another study, genetically SLC1A1-null (Slc1a1−/−) mice had reduced levels of neuronal glutathione and, with aging, developed brain atrophy and behavioral changes." (PMID 30862152, 2019).
Cognitive impairment (7 papers, 2017 to 2025). Abnormal cognition is characterized by deficits in thinking, reasoning, or remembering. "Riluzole improved the cognitive impairment induced by lipopolysaccharide in mice with SLC1A1/EAAT3 (solute carrier family 1 member 1/Excitatory amino acid transporter 3) expression knocked down, suggesting that it may normalise the expression of EAAT3 and glucose metabolism." (PMID 41250235, 2025).